ENSG00000285708 (novel protein)
Gene: Protein-coding gene on chromosome 3 (70,959,226 to 71,754,229, reverse strand). Ensembl gene ENSG00000285708.
Genetic constraint (gnomAD): Loss-of-function variants: 13 observed, 74.1 expected, observed/expected ratio (o/e) 0.18, 90% interval 0.11 to 0.28. Missense variants: 547 observed, 745.7 expected, observed/expected ratio (o/e) 0.73, 90% interval 0.68 to 0.79. Synonymous variants: 320 observed, 279.61 expected, observed/expected ratio (o/e) 1.14, 90% interval 1.04 to 1.25.